UCP2 (uncoupling protein 2)
Diseases named in the same sentence as UCP2 in open-access papers (continued):
Sharing a sentence is not in itself a finding about the gene and the disease.
alcoholism (1 paper, 2013). "Elucidation of the possible molecular mechanisms underlying selective inhibition of the interaction between NMDAR and UCP2 would give a clue for novel strategies to ameliorate neuronal abnormalities related to malfunctions of NMDAR channels in patients with mild and/or severe alcoholism." (PMID 23874988, 2013).
anemia (1 paper, 2009). A reduction in the number of red blood cells, the amount of hemoglobin, and/or the volume of packed red blood cells. "A relationship between UCP2 and the MAPK/ERK pathway has been reported in the case of elevated inflammatory response and inhibition of UCP2 could lead to the development of anemia." (PMID 20204172, 2009).
autism (1 paper, 2021). Persistent deficits in social interaction and communication and interaction as well as a markedly restricted repertoire of activity and interest as well as repetitive patterns of behavior. "We observed genes that were shared across the subgroups such as UCP2 (control, PDD-NOS, autism, and AS) or highly expressed MTF2 (PDD-NOS and AS)." (PMID 33719335, 2021).
axonal neuropathy (1 paper, 2007). Any nerve disorder affecting the axon of a nerve. "These include the NRM (nurim [nuclear envelope membrane protein]), ZDHHC19 (zinc finger, DHHC-type containing 19), UCP2 (uncoupling protein 2 [mitochondrial, proton carrier]) and GAN (giant axonal neuropathy [gigaxonin]) genes." (PMID 17974019, 2007).
benign papilloma (1 paper, 2021). "Lending to the idea that UCP2 is expressed in highly proliferative, embryonic, stem-like states, UCP2 knockout was shown to suppress murine skin carcinogenesis of both benign papilloma and malignant squamous cell carcinoma." (PMID 33763373, 2021).
brain tumors (1 paper, 2021). "In short, UCP2 expression increases with increased WHO tumor-grade and is associated with much poorer prognosis across a cohort of brain tumors." (PMID 33763373, 2021). "A query of the CGGA RNA-seq and the TCGA GBMLGG database demonstrated that UCP2 expression increases with increased WHO tumor-grade and is associated with much poorer prognosis across a cohort of brain tumors." (PMID 33763373, 2021).
cardiac arrest (1 paper, 2019). Cessation of breathing and/or cardiac function. "Whether UCP play a protective or pathophysiologic role in the heart post-cardiac arrest is largely unexplored, though there is emerging evidence that uncoupling protein 2 (UCP2) may be protective in the septic myocardium." (PMID 31323783, 2019).
Cirrhosis (1 paper, 2011). A chronic disorder of the liver in which liver tissue becomes scarred and is partially replaced by regenerative nodules and fibrotic tissue resulting in loss of liver function. "Only a minority of heavy drinkers develop cirrhosis so that comparison of the frequency of the various UCP-2 polymorphisms in patients with cirrhosis with those without cirrhosis in a population of alcohol drinkers would be of interest." (PMID 21547084, 2011).
colitis (1 paper, 2021). Inflammation of the colon. "This study found that JUG inhibited Ucp2 and p-p65 while activated Nrf2 in colitis." (PMID 34421890, 2021).
complication (1 paper, 2016). Any disease or disorder that occurs during the course of, or because of, another disease, treatment, or procedure. "We conclude that UCP2 induction may represent a novel experimental therapeutic intervention in diabetic vascular complications." (PMID 27128320, 2016).
COVID-19 (1 paper, 2022). A disease caused by infection with severe acute respiratory syndrome coronavirus 2. "In this regard, in LPS-incubated HPMEC, the protein expression level of UCP-2 protein was markedly enhanced by COVID-19 spike S1+S2 subunits." (PMID 36438904, 2022). "Moreover, rivaroxaban also prevented the increase in UCP-2 expression observed in HPMEC incubated with COVID-19 spike S1+S2 subunits and LPS." (PMID 36438904, 2022). "However, a significant increase in UCP-2 protein expression was observed when COVID-19 spike S1 and S2 subunits were added to LPS-incubated HPMEC." (PMID 36438904, 2022). "As conclusion, in LPS-incubated HPMEC, COVID-19 spike S1 and S2 subunits promoted greater reduction of ΔΨm and increase of cytochrome c oxidase and LDH activities accompanied of increase of UCP-2 expression suggesting a possible energetic metabolism change from aerobic towards anaerobic situation." (PMID 36438904, 2022). "In the HPMEC and in the absence of LPS, COVID-19 S1+S2 spike subunits by themselves failed to modify UCP-2 expression." (PMID 36438904, 2022). "However, it is important to point out that without preinflammatory condition, COVID-19 spike subunits by themselves failed to modify UCP-2 expression in HPMEC suggesting that only under preinflammatory conditions, COVID-19 spike subunit protein may modify mitochondrial activities." (PMID 36438904, 2022).
developmental delay (1 paper, 2020). "Four genes (UCP2, UCP3, SCAPER, and TSHR) are related to the body weight (HP:0004324 and HP:0004323), and four genes (C2CD3, UCP2, ZMYND11, and TSHR) are involved in modulating the phenotype of globe developmental delay (HP:0001263)." (PMID 32973871, 2020).
Encephalopathy (1 paper, 2021). Encephalopathy is a term that means brain disease, damage, or malfunction. "Bezafibrate, a pan-PPAR agonist, can significantly increase the levels of CD36, ACOX1, CPTI, CPT II, and uncoupling protein-2/3 (UCP-2/3), improve mitochondrial ΔΨm, restore intracellular ATP level, and further improve IAV-associated encephalopathy." (PMID 34540999, 2021).
endotoxemia (1 paper, 2015). "Similarly, myocardial mRNA content of both UCP2 and UCP3 were increased in LPS-induced endotoxemia in rats, and increased myocardial mRNA and protein expression of UCP2 was observed in a canine model of endotoxin-induced shock associated with decreased phosphocreatine/ATP ratios." (PMID 26247933, 2015).
Fanconi anemia (1 paper, 2023). Fanconi anemia (FA) is a hereditary DNA repair disorder characterized by progressive pancytopenia with bone marrow failure, variable congenital malformations and predisposition to develop hematological or solid tumors. "Treatment with P110, a specific inhibitor of DRP1, shows a partial mitochondrial function recovery and the decrement of DRP1 and UCP2 expression, suggesting a pivotal role of the mitochondrial dynamics in the etiopathology of Fanconi anemia." (PMID 37047537, 2023).
gout (1 paper, 2022). A condition characterized by painful swelling of the joints, which is caused by deposition of urate crystals. "To further evaluate the possible role of CPT2 in gout, we first assessed the interaction between UCP2 and wild-type CPT2, then determined the effect of the p.R631C mutation on this interaction." (PMID 35372350, 2022).
hematoma (1 paper, 2023). A hematoma is a collection of blood from a vascular structure into an extravascular space. "Complex I-derived superoxide subsequently activates uncoupling protein 2 (UCP2) to decrease MMP after erythrocytosis, which promotes continual phagocytosis and hematoma clearance following ICH." (PMID 37601043, 2023).
hepatoblastoma (1 paper, 2019). Hepatoblastoma (HB) is a malignant hepatic tumor and is the most common pediatric liver cancer. "The mitochondrial uncoupling protein 2 (UCP2) has been identified as a target of miR-214 in the hepatoblastoma cell line HuH6." (PMID 30909459, 2019).
hyperhomocysteinemia (1 paper, 2022). A serious metabolic condition caused by mutations in the MTHFR gene, medications, or nutritional deficiency. "Only one study reported a significant correlation between the 45 bp ins/del of UCP2 with hyperhomocysteinemia, a known risk factor for IS, in a Caucasian population." (PMID 35629388, 2022).
hyperlipemia (1 paper, 2024). "It is possible that hyperlipemia (in obese patients) causes also a superoxide-mediated activation of UCP-2 and thus a loss in insulin secretion (UCP-2 knockout mice maintain insulin secretion after long-term incubation with palmitic acid)." (PMID 39201524, 2024).
hypothyroidism (1 paper, 2023). Abnormally low levels of thyroid hormone. "Uncoupling protein 2 (Ucp2) is reduced in cases of impaired ovulation associated with fetal exposure to hypothyroidism and mediates apoptosis, gap junction integrity, and progesterone synthesis in cumulus cells." (PMID 37157877, 2023).
infertile (1 paper, 2021). "The genotype frequencies of UCP2 G-866A, MnSOD C47T, and CAT C-262T were found to be significantly different among the fertile subjects, the infertile subjects with more than 50% motility, and the infertile subjects with less than 50% motility." (PMID 34527175, 2021). "The genotype frequencies of UCP2 G-866A, MnSOD C47T, and CAT C-262T were found to be significantly different among the fertile subjects (control group), infertile subjects with more than 50% motility, and infertile subjects with less than 50% motility." (PMID 34527175, 2021).
influenza (1 paper, 2023). An acute viral infection of the respiratory tract, occurring in isolated cases, in epidemics, or in pandemics; it is caused by serologically different strains of viruses (influenzaviruses) designated A, B, and C, has a 3-day incubation period, and usually lasts for 3 to 10 days. "Additionally, genes involved in cell processes and cytoskeletal structural elements were upregulated in activated cTfh cells compared to resting cells following influenza vaccination: ELMO2, ACTG1, STMN1, ANP32B, UCP2, and HMGB3." (PMID 37063867, 2023).
invasive breast ductal carcinoma (1 paper, 2011).
liver cancer (1 paper, 2022). An epithelial or non-epithelial malignant neoplasm that arises from the liver. "This was supported by the enrichment of heat shock proteins and thermoprotectant solutes that protect the protein structures in high temperatures, and by the overexpression of the mitochondrial uncoupling protein UCP2 in liver cancer cells." (PMID 35780250, 2022). "This was confirmed by knocking down UCP2 expression in human hepatic cancer HEPG2 cells, leading to an increase in the mitochondrial membrane potential and ATP/ADP ratio, and a corresponding decrease in mitochondrial temperature." (PMID 35780250, 2022). "Further experiments showed that peroxisome proliferator-activated receptor α (PPAR), the activator of UCP2, was overexpressed in liver cancer cells compared to normal liver cells." (PMID 35780250, 2022).
liver diseases (1 paper, 2025). "Uncoupling protein 2 (UCP2) rs695366-G (HR for steatotic liver disease: A/G 0.63, p = 0.002, G/G HR: 0.50, p = 0.04) appeared as the most critical genetic risk factor for steatotic liver diseases post-liver transplantation." (PMID 40507973, 2025).
lung diseases (1 paper, 2016). "A better understanding of the role of UCP2 in inflammation may be promising for developing new treatments for lung diseases in the future." (PMID 27057102, 2016).
malignant glioma (1 paper, 2022). A grade III or grade IV glioma arising from the central nervous system. "The presence of regional STC1 uncouples the oxidative phosphorylation process by increasing the expressions of mitochondrial UCP2, which is a valuable biomarker for the diagnosis of malignant glioma for the assessment of postoperative prognosis." (PMID 36713509, 2022).
metabolic acidosis (1 paper, 2011). "Similarly, loss-of function UCP-2 polymorphisms could also lead to increased risk of metabolic acidosis, due to a relative switch of ammonia detoxification from glutamine synthesis (centrilobular and proton-neutral) to ureogenesis (periportal and proton-generating)." (PMID 21547084, 2011).
migraine (1 paper, 2022). "Lastly, variability in the CAT, GSTP1 and UCP2 genes were associated with sleep/weather changes, alcohol consumption and physical exercise, respectively, as migraine triggers." (PMID 36698892, 2022). "Association analysis of the UCP2 rs660339 variant with physical activity as migraine trigger." (PMID 36698892, 2022).
mood disorder (1 paper, 2017). A cognitive disorder a disturbance in which the person's mood is hypothesized to be the main underlying feature. "An interesting effect of UCP2 polymorphisms on lifetime occurrence of mood disorders requires independent replication." (PMID 28771482, 2017). "Due to the significant effects of UCP2 polymorphisms on lifetime risk of mood disorders in men in this sample, we carried out two different analyses of the neuroimaging data." (PMID 28771482, 2017). "However, we observed a significant effect of UCP2 polymorphisms on the occurrence of mood disorders in men in this sample." (PMID 28771482, 2017). "Therefore, UCP2 polymorphisms might be genetic risk factors that affect lifetime occurrence of less severe mood disorders particularly in men." (PMID 28771482, 2017). "In the second analysis, we only included male participants and investigated main effects of UCP2 haplotype group and lifetime occurrence of mood disorders and their interaction." (PMID 28771482, 2017). "Using this metric, we were not able to replicate the significant effect of UCP2 polymorphisms on occurrence of mood disorders in the larger sample." (PMID 28771482, 2017).
multiple myeloma (1 paper, 2021). "Studies on the genetic background of patients with multiple myeloma (MM) have been increasing; two important factors considered in such works are uncoupling protein-2 (UCP-2) and nuclear receptor subfamily 3 group C member 1 (NR3C1)." (PMID 34481515, 2021).
neovascular glaucoma (1 paper, 2023). "Moreover, a study that investigated the TM of patients with neovascular glaucoma who underwent trabeculectomy demonstrated that UCP2 was significantly decreased in the TM cells of neovascular glaucoma patients compared to the control group." (PMID 37566048, 2023).
ovarian tumors (1 paper, 2011). "Eighty percent of grade 1, 96% of grade 2 and 78% of grade 3 ovarian tumors strongly expressed UCP2 in more than 10% of cells (IHC score 2 and 3)." (PMID 21935467, 2011). "In contrast, UCP2 was over-expressed in more than 80% of breast and ovarian tumors." (PMID 21935467, 2011).
paraganglioma (1 paper, 2020). A benign or malignant neoplasm arising from paraganglia located along the sympathetic or parasympathetic nerves. "In pheochromocytoma and paragangliomas there is no data about the expression and role of mitochondrial uncoupling protein 2 (UCP2) which has been suggested to be a metabolic sensor of cells under nutrient shortage." (PMID 32150977, 2020).
prion disease (1 paper, 2025). A transmissible disease that is caused by a protein that is able to induce abnormal folding of normal cellular proteins, leading to characteristic spongiform brain changes, which are associated with neuronal loss without an inflammatory response. "Specifically, in our study, exogenous irisin protected against mitochondrial damage caused by oxidative stress via the UCP2-AMPK signaling pathway, which is crucial for the treatment of prion diseases." (PMID 39900919, 2025). "Specifically, in prion disease models, irisin’s neuroprotective effects may rely on the UCP2/AMPK/Nrf2 axis rather than the AKT/ERK1/2 pathway." (PMID 39900919, 2025).
retinal degeneration (1 paper, 2022). Degeneration of the retina. "In addition to regulation by a number of growth factors, including the neuroprotective factors LIF and PEDF, small molecule activators of UCP2 have been found to reduce mitochondrial ROS production and protect against cell death both in culture and animal models of retinal degeneration." (PMID 35628482, 2022).
retinal ischemia (1 paper, 2019). A ischemic disease that involves the retina. "PPAR-γ agonism with pioglitazone is sufficient to decrease RGC loss following optic nerve crush in rats or retinal ischemia/reperfusion injury in mice, suggesting that glial Ucp2 expression may be protective against more acute retinal insults." (PMID 30906248, 2019).
rhabdomyosarcoma (1 paper, 2019). A rare aggressive malignant mesenchymal neoplasm arising from skeletal muscle. "Polyclonal antibodies can cross-react with structurally-related molecules so it is possible that staining with the anti-UCP1 antibody of malignant tumour cells in some non-adipose sarcomas could represent a cross-reaction with a UCP1 homologue, such as UCP2 and/or UCP3 in rhabdomyosarcomas." (PMID 31114671, 2019).
sarcopenia (1 paper, 2022). Progressive decline in muscle mass due to aging which results in decreased functional capacity of muscles. "IGFBP3 and UCP2 are both related to muscle phenotypes associated with sarcopenia, an age-related loss of muscle function." (PMID 36003146, 2022).
Shock (1 paper, 2018). The state in which profound and widespread reduction of effective tissue perfusion leads first to reversible, and then if prolonged, to irreversible cellular injury. "UCP2 (mRNA and protein expression) caused decreased cardiac mechanical efficiency (hydraulic work/myocardial oxygen consumption) in a septic shock model in rats and was associated with an impaired myocardial energy metabolism and decreased ATP levels in a canine endotoxin shock model." (PMID 29576853, 2018).
skin aging (1 paper, 2022). The gradual irreversible changes in structure of skin that occur as a result of the passage of time.. "Both IGFBP2 and UCP2 are associated with miR-124, which has been shown to increase in senescent skin and upon UVB-irradiation (type B ultraviolet), indicating a possible role of miR-124 in UVB-induced skin aging." (PMID 36289702, 2022).
systemic lupus erythematosus (1 paper, 2014). An autoimmune multi-organ disease typically associated with vasculopathy and autoantibody production. "For example, the single nucleotide polymorphism within the UCP2 gene was identified to associate with many chronic inflammatory diseases including RA and systemic lupus erythematosus (SLE)." (PMID 24551036, 2014).
thrombophilia (1 paper, 2023). A condition characterized by an abnormally high level of thrombi. "CD320, RTEL1, UCP2, APOA5 and PROZ participate in healthy-specific or disease-specific subnetworks involving thrombophilia-annotated genes and are related to general thrombophilia mechanisms according to the literature." (PMID 37098010, 2023).
vascular dementia (1 paper, 2022). A degenerative vascular disorder affecting the brain. "SMYZG activates and regulates four main signaling pathways relevant to vascular dementia including the AMPK/PPARα/PGC-1α/UCP2, Nrf2/HO-1, HIF-1/VEGF/Notch, and VEGF/Flk-1/p8 MAPK pathways." (PMID 36507350, 2022).
Ventricular arrhythmia (1 paper, 2022). "Phenotypes of UCP2 knockout mice showed increased susceptibility to Ca2+-mediated ventricular arrhythmias, suggesting that UCP2 plays an important role in cardiac electrophysiology." (PMID 35328444, 2022).
visceral leishmaniasis (1 paper, 2022). A severe form of leishmaniasis characterized by irregular bouts of fever, substantial weight loss, swelling of the spleen and liver, and anemia (which may be serious). "Uncoupling protein 2 negatively regulated mitochondrial ROS generation to regulate the production of cytokines in experimental visceral leishmaniasis." (PMID 35355995, 2022).